CD4 (CD4 molecule)
Diseases named in the same sentence as CD4 in open-access papers (continued):
Sharing a sentence is not in itself a finding about the gene and the disease.
tumor (continued). "Additionally, the depletion of TGFβRII from CD4 + T cells reprogram the tumor vasculature and triggers cancer cell death, which in turn inhibits cancer progression in mice." (PMID 38890701, 2024). "Similarly, IFN-γ+ CD4+ T cells in spleens were significantly increased up to nine-fold compared to the levels in untreated tumor-bearing mice." (PMID 38932362, 2024). "Our findings reveal a significant correlation between the expression of ARHGAPs genes and the immune markers of tumor-associated macrophages (TAM), M1 and M2 macrophages, as well as subgroups of CD4 + T cell differentiation, including Th1, Th2, Tfh, Th17, and Treg cells." (PMID 38783033, 2024). "In a dose-escalation study of DNX-2401 in patients with newly diagnosed DMG, it was found in tumour tissue from patients that immune cell infiltration of CD4+ and CD8+ T cells was scarce while CD11b+ myeloid cells were the most abundant immune population upon diagnosis." (PMID 38732225, 2024). "Castalagin improved the CD8+/FOXP3+CD4+ ratio in the tumor microenvironment." (PMID 38361936, 2024). "Besides, more CD8+ T, CD3+ T, CD4+ T and NKp46+ NK cells are found at the edge of tumors compared to tumor centers." (PMID 37072770, 2023). "Moreover, the differences were more pronounced in the microenvironment adjacent to the tumor cells due to CD4+ naïve T cells, M2 macrophages, and eosinophils." (PMID 36674951, 2023). "In hepatocellular carcinoma, increased percentage of tumor-infiltrating PD-1+ BTLA+ CD4+ T lymphocytes was observed when compared to those from tumor-free regions from the same patient, pointing out a role of the tumor microenvironment (TME) in this dysregulation." (PMID 37649037, 2023). "CD4+ lymphocytes have been found to be abundant in proximity of the tumor." (PMID 37296886, 2023). "Furthermore, CD4+ T cells have been shown to modulate tumor metabolism, leading to increased TNF-α-dependent oxidative stress and subsequent tumor cell death." (PMID 37686677, 2023). "Tumor-specific CD4+ T cell responses often target self-derived epitopes." (PMID 37513965, 2023). "Furthermore, CD4+ T cells can help activate CD8+ T cells by delivering tumor antigens to CD8+ T cells or by triggering the production of cytokines and suppressor molecules." (PMID 37513975, 2023). "In addition, some immune subpopulations are repolarized anti-tumor ones with elevated M1/M2-skewed macrophages and conventional CD4+ T/Treg cells." (PMID 37173915, 2023). "Similarly, the blood and tumor tissues of patients with bladder cancer treated with anti-CTLA-4 antibodies showed a higher expression of ICOS CD4+ T cells." (PMID 38328405, 2023). "Naïve CD4 T cells can be polarized towards different helper subsets, which can drastically affect the antitumor response through interactions with other cell types and the tumor microenvironment." (PMID 36980536, 2023). "Thus, the function of SLC35A2 is closely related to the infiltration of CD4+T cells and macrophages in the tumor microenvironment, which is expected to serve as a potential immune-related marker in STAD tumors." (PMID 37467193, 2023). "CD4+ T cells, though less frequent, also contribute to tumor control." (PMID 37841280, 2023). "Therefore, GC patients with GPC3high CAFs closely correlated with the effect of PD-1 blockage therapy and the activity of tumour infiltrated CD4+ and CD8+ T cells." (PMID 37036308, 2023). "The fact that the PI3K pathway is activated universally in T cells in response to IL-2 involvement may explain why IL-2 secreted by CD4+ T cells at the tumor site induces CXCR3 expression in various T- cell subsets." (PMID 38104126, 2023). "Furthermore, diminished PD-L1 expression increased the numbers of CD4 + tumor-infiltrating lymphocytes, resulting in robust CD4 + T-cell-mediated tumor rejection." (PMID 37993880, 2023).
tumor (continued). "In contrast to solid tumors, the likely mechanism of action of PD-1 blockade in cHL involves modulation of the tumor microenvironment (TME) with rapid clearance of CD4+ regulatory T cells and PD-L1+ macrophages and withdrawal of pro-survival signals rather than activation of CD8+ cytotoxic T cells." (PMID 37760478, 2023). "Furthermore, in both humans and mice the presence of lipogranulomas containing CD44+-macrophages accompanies the expansion of CD4+/FOXp3+ Tregs and tumor burden, suggesting a possible contribution of NAMs in promoting an immunosuppressive microenvironment." (PMID 36691794, 2023). "The ratio of IL10 to IFNγ produced by the Tr1-like cytotoxic CD4 T cells could be a key determinant in whether Tr1-like cytotoxic CD4 T cells have a net pro-tumor or anti-tumor impact." (PMID 37654482, 2023). "It has been reported that patients with OSCC have a higher number of CD4 + Th17 cells in the tumor and blood, which may promote tumor growth." (PMID 37221555, 2023). "The association of high pretreatment frequency of CD103+CD8+ and CD4+ T cells with major pathological response to therapy suggests that responding patients are likely to have an antecedent, nascent, albeit ineffective, anti-tumor immune response." (PMID 38114518, 2023). "However, CD4 T helper cells are gaining attention for their direct anti-tumor action as well as their ability to license and sustain CTLs for killing." (PMID 37266839, 2023). "Similarly, GrB-producing CD4 + T cell responses predict the development of severe host immune response, worsening inflammation, and tumor progression." (PMID 38072840, 2023). "Both CD3 + /CD4 + and CD3 + /CD8 + T-cell as well as CD68 + /CD163 + hot tumours were significantly associated with high PD-L1 expression scores, which might be relevant for therapy of squamous bladder cancer with pembrolizumab." (PMID 36726072, 2023). "We analysed the correlation of the ICD risk signature with the OS tumour microenvironment and found that the risk score was negatively correlated with endothelial cells, B cells, CD4 T cells, CD8 T cells, and macrophages." (PMID 37277499, 2023). "Tumor rechallenge significantly stimulated CD4+ T cells expression of TNFα." (PMID 37407600, 2023). "We further observed the proximity of CD4+ CTLs and apoptotic tumor cells." (PMID 38077321, 2023). "Moreover, there was a significant increase in the Th17 (RORγt+ in CD4 + ) and activated and proliferating Th17 cells (RORγt+Ki67+CD44+ in CD4+) within the tumour in the Vacc DC-treated mice as compared to all the other groups." (PMID 37660049, 2023). "Taken together, tSNE analysis corroborated the finding that Vactosertib increases anti-tumor immunity against OS in TME through the accumulation of CD4+ T cells, CD8+ T cells and NK cell while suppressing the number of Tregs, MDSCs and M2-like TAMs in the OS TME." (PMID 37066414, 2023). "Radiotherapy in combination with HERA-CD40L treatment resulted in an increase in detected intratumoral CD4+/8+ T cells compared to RT alone and, additionally, the repolarization of TAMs was also observed, resulting in an inhibition of tumor growth in a TRAMP-C1 mouse model." (PMID 37304285, 2023). "PDCD1 is mainly expressed by CD4+ and CD8+ T lymphocytes, whereas its ligand, CD274, is widely expressed in various cell types including activated lymphocytes, fibroblasts, tumor-associated macrophages and tumor cells." (PMID 36979400, 2023). "However, consistent with the results of this study, the absence of MHC Class II expression has been reported in SCLC, suggesting reduced presentation of tumor antigens to CD4+ T cells in SCLC." (PMID 37958393, 2023). "However, there are studies demonstrating anti-tumour activity of CD4+Th2 cells particularly in collaboration with tumour-infiltrating granulocytes, such as eosinophils." (PMID 36790524, 2023). "Prior to our study, an outstanding question of recent clinical findings was whether CD4 CTLs are important to tumor control in patients." (PMID 37185301, 2023).
tumor (continued). "We additionally explored the ratio of CD8+ to CD4+ T cells across tumor subtypes." (PMID 37492101, 2023). "However, in GC tissues with low (+) C5aR1 levels, fewer CD8+ and CD4+ T cells were clustered in the peripheral tumor stroma, and a higher number of immune cells infiltrated the stroma of the tumor parenchyma." (PMID 36508191, 2023). "In DLBCL, the elevated number of CD4+ cells in the tumor environment predicts a better outcome." (PMID 37009375, 2023). "Here we describe a versatile multiparametric flow cytometry method to assess the polyfunctionality of tumor antigen-specific CD4+ and CD8+ T cell responses based on their production of multiple cytokines after short-term ex vivo restimulation with relevant mouse tumor epitopes." (PMID 37090730, 2023). "Additionally, CXCL13+ TH1-like cells (T05) were also enriched in tumor sites, whereas CD4+ANXA1+ TCM (T02) and CX3CR1+ Teff cells (T04 and T09) were mainly detected in blood and ascites." (PMID 37488416, 2023). "Our data suggest that CD4 CTLs might be induced by tumor vaccination and that alloantigen-specific CD4 CTLs can potentially be harnessed for the development of T-cell therapies." (PMID 37185301, 2023). "An analysis of tumor‐infiltrating immune cells showed statistically significant differences between the low‐ and high‐risk groups in nine groups of immune cells, including CD8 and CD4 memory T cells." (PMID 36726348, 2023). "However, in order to achieve effective anti-tumor immunity, the complementary CD4+ T cells are also necessary." (PMID 37180714, 2023). "In addition, under the induction of TGF-β1 secreted by tumor cells, cells produce more adenosine, which shows obvious immunosuppressive effect on CD4 + T cells through adenosine-mediated pathway, and promotes tumor progression and metastasis." (PMID 37600023, 2023). "have shown that tumor-infiltrating CD4+Treg express CCR4 in lymphoma and gastric cancer." (PMID 38250084, 2023). "Collectively, these data demonstrate that IL21-anti-HSA and anti-PD-1 mAb synergistically enhance a tumor site–focused CD4+ T cell–mediated antitumor immune response through promoting the hyperactivated/exhausted CD4+ T-cell subtype and CD4+ T-cell clonal expansion." (PMID 37546701, 2023). "Tumor microenvironment and immune cell infiltration analysis showed that the immune and matrix scores were lower in C1 tumors, and the infiltration abundance of immune cells such as CD4 + T, CD8 + T, and B cells was also lower." (PMID 37234773, 2023). "CD4 T cells also contribute to the cytotoxic anti-tumor response." (PMID 37033927, 2023). "We proposed that adoptively transferred CD4+ T cells and injections of synthetic nucleic acids direct a strong TH1-associated pathogen defence mechanism that also engages mononuclear phagocytes towards tumour destruction." (PMID 37316667, 2023). "Third, and more importantly, anti-tumor immunity could be transferred to syngeneic naïve recipients by adoptive cell transfer of immune cells and particularly by CD4+ Th cells." (PMID 37467968, 2023). "Importantly, MHC-II+ tumor cells preconditioned with IFN-γ were unable to stimulate CD4+ TILs as measured by IFN-γ secretion." (PMID 36512410, 2023). "CD4+ memory T-cells can proliferate and differentiate faster after receiving antigen stimulation for a second time, and the differentiated subpopulation exerts anti-tumor effects by secreting cytokines or activating CD8+ T lymphocytes." (PMID 37059591, 2023). "After facing tumor antigens, immature CD4+ T cells are made active and polarized." (PMID 37605131, 2023). "This enrichment could potentially augment the tumor infiltration of CD4 + lymphocytes, alongside activated subsets of CD4 cells expressing KI67 + and CD69 + markers throughout the course of radiation therapy." (PMID 38033576, 2023). "However, motifs were found to be useful for manual annotation of putative tumor-specific sequences, especially among CD4+ TILs." (PMID 37600765, 2023).
tumor (continued). "The mean value of CD4+ lymphocytes was 12.04 in the tumor center and 40.79 at the invasion front." (PMID 36836239, 2023). "This increase was approximately 2-fold of the CD4+ population found in parental tumours." (PMID 37153626, 2023). "Additional studies in an orthotopic MB49 bladder cancer model showcased significant tumor regression with NHS-IL12 associated with decreases in immunosuppressive tumor TGFβ levels, MDSCs and TAMs, while increasing M1-macrophages and CD4+ and CD8+ T cell responses." (PMID 38260854, 2023). "Moreover, risk scores were negatively related to the expression of CD274, CTLA4, ICOS, LAG3, PDCD1, and PDCD1LG2 and negatively correlated with CD8+, CD4+, and Treg tumor-infiltrating immune cells." (PMID 37674251, 2023). "Moreover, we found that GPR43 deficiency in Gpr43−/− mice (confirmed in CD8+ and CD4+ T cells and in B cells by Gpr43 mRNA levels) abolished TVA diet-dependent reduction of the tumour growth observed in littermate control mice." (PMID 37993715, 2023). "MEX3B was positively correlated with tumour purity and CD4+ T cell and macrophage infiltration." (PMID 36507941, 2023). "In PD-L1/LAG-3 double knock-in mice bearing human PD-L1 knock-in MC3 tumors, IBI323 exhibited stronger antitumor activity than each parental antibody, and these antitumor responses were associated with an increase in the number of tumor-specific CD8+ and CD4+ T cells." (PMID 37670328, 2023). "Moreover, we observed increases in effector memory T cells (Tem) and central memory T cells (Tcm) in CD8+ and CD4+ T cell subsets in splenocytes from MC38 tumour-bearing mice treated with PGN4.9 nanoadjuvant." (PMID 37735462, 2023). "While CD4 T cells have been typically relegated to the ‘supporting cast’ of anti-tumor immune cells, studies in the last decade or so have shown that CD4 T cells with cytolytic properties are capable of being the main tumor-killing cell type in effective anti-tumor immune responses." (PMID 37654482, 2023). "Additionally, preclinical studies indicate ROS-dependent cell death of hepatic CD4+ T cells can occur leading to impaired anti-tumor surveillance." (PMID 37608898, 2023). "Therapeutic CD4+/CD8+ T cell NeoAg vaccination produced a modified tumor microenvironment (TME) with increased numbers of NeoAg-specific CD8+ T cells existing in progenitor and intermediate exhausted states enabled by combination ICB-mediated intermolecular epitope spreading." (PMID 37655661, 2023). "The design aimed to activate both MHC-I CD8+ and MHC-II CD4 T-cell functions because the activation of CD4+ cells plays important roles in promoting the DC- meditated cross-presentation of neoantigens and TAAs on the tumor surface and further enhances the antitumor effect of CD8+ T cells." (PMID 36761724, 2023). "Despite this similar response to the presence of a tumor, we found that the immune composition of the tumor-draining lymph node was still markedly different between young and aged mice, with a reduced frequency of both CD4+ and CD8+ T cells and an increased frequency of B cells in the aged cohort." (PMID 37920465, 2023). "The TIME comprises a diverse range of CD45+ leucocytes, collectively called tumour infiltrating leucocytes (TILs), which includes CD4+ and CD8+ T-cells, B-cells, tumour-associated macrophages, dendritic cells, myeloid-derived suppressor cells and natural killer cells." (PMID 37013636, 2023). "Additionally, the activity of CD4+ Th1 cells influences tumor-killing promotion by NK and M1-type macrophages." (PMID 38067231, 2023). "Additionally, intracellular (ic) enzymatic proximity labeling has been used to monitor interacting cells within a defined receptor–ligand pair, such as CD40:CD40L between DCs and CD4+ T cells in the tumor-draining lymph node." (PMID 37871202, 2023). "In addition, tumor-infiltrating Tregs can arise from circulating naive CD4+ T cells that differentiate into Treg cells in cancer tissues." (PMID 37124519, 2023).
tumor (continued). "Cross-reactive CD4+ or CD8+ T cells primed against a bacterial antigen may be able to generate an anti-tumor immune response in cells with the same antigen, in addition to neoantigens." (PMID 38275827, 2023). "The positive correlation of the HLA-DPA1/CD4 expression with some immune cells with anti-tumor effects such as NK cells may explain this phenomenon." (PMID 36627705, 2023). "Notably, clinical responses correlated with a decrease in circulating CD4+ regulatory T cells and an increase in CD4+ effector T cells, as well as with the infiltration of the tumor microenvironment by cytotoxic CD8+ T cells." (PMID 37834466, 2023). "Notably, CD4+ T cells aid in the priming of tumor-specific CD8+ T cells by licensing antigen-bearing DCs in a CD40L-dependent manner." (PMID 36512410, 2023). "Moreover, tumor-derived galectin-1 was demonstrated to attenuate the expansion of the CD4+CD25+FOXP3+ Treg cells in human Hodgkin lymphomas." (PMID 37047471, 2023). "CD4+ regulatory T cells (Tregs) are highly immunosuppressive cell subsets that, when overexpressed, can hinder immune surveillance of cancer, prevent effective anti-tumor immune responses, and promote tumor progression." (PMID 37234164, 2023). "In a NSCLC preclinical study, the depletion of Tregs via an antibody targeting CD25, a surface protein found on a majority of CD4+ Tregs, synergized with carboplatin chemotherapy and significantly extended the survival of tumor-bearing mice compared to chemotherapy alone." (PMID 37830618, 2023). "Furthermore, we examined the spatial profiles of B cells at the protein level by mIHC and observed abundant CD19+ B cells localized in the tertiary lymphoid structure (TLS) of EBV (+) GC tumours that colocalized with CD4+ and CD8+ T cells." (PMID 37735150, 2023). "Furthermore, analysis of immune-signature revealed that tumour environments of ARID1A-deficient tumours were infiltrated with specific subtypes of immune cells, such as subsets of CD4+, CD8+ T cells and NK cells, type 17 T-helper cells (Th17), and so on." (PMID 37568604, 2023). "By contrast, CD4+ Th cells from CAR T-vax-treated mice upregulated genes associated with Th1 function (Ifng, Cxcr3) and self-renewal (Slamf6, Tcf7), suggesting that the vaccine may also promote anti-tumor phenotypes among CD4+ TILs." (PMID 37413990, 2023). "CD8+ T cells are known to have the ability to directly eliminate tumor cells, making them the preferred immune cells for targeting tumors, However, in order to achieve effective anti-tumor immunity, the complementary CD4+ T cells are also necessary." (PMID 37180714, 2023). "Meanwhile, many more CD4+ cells and CD8+ cells were observed in the deep tumor environment with unlocked Pres treatments, suggesting that significantly more CD4+ cells and CD8+ cells had been infiltrated into the deep tumor environment through loosened tumor structure." (PMID 37875395, 2023). "Systemic administration of SC144 loaded in HABN (SC144@HABN) induces apoptosis and ICD of tumor cells, increases the ratio of M1-like to M2-like macrophages, and decreases the frequency of myeloid-derived suppressor cells and CD4+ regulatory T-cells, while promoting anti-tumor CD8+ T-cells." (PMID 37553327, 2023). "Alternatively, transducing CD4 T cells with low-affinity CAR constructs or with CARs targeting antigens expressed at low levels could reduce their activation levels on tumor encounter, thus mitigating the consequent development of lethal toxicities." (PMID 36593069, 2023). "Additionally, the U@ZIF‐Gel microspheres induced tumor cell apoptosis, re‐polarized M2 macrophages to M1 macrophages, and increased the ratio between CD8/CD4 T cells in tumor tissues." (PMID 37693055, 2023). "Interestingly, xCT depletion in 4T1 tumor cells resulted in a significant increase in CD4+ T, CD8+ T, B, and NK cells, which are important players in the antitumor immune response, and in fewer PMN-MDSC, in the lungs." (PMID 37770957, 2023).